TLR5 (toll like receptor 5)
Diseases named in the same sentence as TLR5 in open-access papers (continued):
Sharing a sentence is not in itself a finding about the gene and the disease.
tetanus (1 paper, 2022). A serious infectious disorder that follows wound contamination by the Gram-positive bacterium Clostridium tetani. "This clinical trial assessed AB titers after a single booster of commercial tetanus-diphtheria (Td) vaccine in 40 males randomized as 15 to Td alone and 25 to Td combined with the TLR5 adjuvant, Entolimod (Ent)." (PMID 36298456, 2022).
Type 1 diabetes (1 paper, 2024). "Further investigation into the role of TLR5 in DC development and autoimmune diabetes may give additional insights into the pathogenesis of Type 1 diabetes." (PMID 38482010, 2024). "It is conceivable that altered TLR5 signaling may play a role in the increased TNFα levels in patients with type 1 diabetes." (PMID 38482010, 2024).
uveal melanoma (1 paper, 2016). A melanoma derived from melanocytes of the uveal tract. "The goal of this study was to assess the antitumor activity of the flagellin-based TLR5 agonist entolimod against hepatic micrometastases that spontaneously develop in mice with orthotopic uveal melanoma tumors in the eye." (PMID 26655090, 2016).
uveitis (1 paper, 2022). An inflammatory process affecting a part of or the entire uvea. "First, the specific contribution of tlr5 orthologs in zebrafish uveitis model is not yet clarified due to lack of available commercial antibodies against this molecule and its downstream signaling effectors in zebrafish, which awaits further investigation." (PMID 36532084, 2022).
infection (185 papers, 2004 to 2026). The state of being infected such as from the introduction of a foreign agent such as serum, vaccine, antigenic substance or organism. "During acute P. aeruginosa infection in mice, TLR5 signaling is associated with the clearance of low amounts of bacteria and the recruitment of neutrophils to the site of infection." (PMID 39670709, 2025). "Given that E. coli and flagellate-stimulated TLR5 are implicated in the activation of quiescent FV3 infection, the homologous ligands were further used to determine the stimulation specificity of TLR5 in mandarin fish WBCs." (PMID 39772201, 2024). "To study the contribution of TLR5 in the host defense against leptospires, we infected WT and TLR5 deficient mice with pathogenic L. interrogans and tracked the infection by in vivo live imaging of bioluminescent bacteria or by qPCR." (PMID 32849665, 2020). "In the present study, during infection, the deficient strain of fliA showed blocked flagellar synthesis, and expression of Toll-like receptor 5 (tlr5) was decreased, as expected." (PMID 31614635, 2019). "Here, we found a significant effect of TLR1 and TLR5 alleles on the risk of infection with Bartonella sp." (PMID 29849060, 2018). "We found significant associations between allele TLR5*02 and susceptibility to infection with Bartonella sp., a flagellate bacteria." (PMID 29849060, 2018). "The C/T (TLR5 R392StopCodon) and T/T (TLR9 -1486C/T) genotypes appear to be risk factors for infection by P. vivax (TLR5: C/C vs. C/T [OR: 2.116, 95% CI: 1.054–4.452, p = 0.031]; TLR9: C/C vs. T/T [OR: 1.919, 95% CI: 1.159–3.177, p = 0.010]; respectively)." (PMID 28850598, 2017). "Considering the stimulatory effects of both CFT073 and F11 on the transcription of TLR5 and associated signaling factors, we wished to determine the contributions of the FliC variants to the infection process and host responses." (PMID 27303721, 2016). "TLR5 is an important innate immune regulator of inflammation in infections, including those caused by Salmonella, Legionella, Clostridium, Pseudomonas, E. coli, and others." (PMID 24959742, 2014). "A wide range of acute phase protein encoding genes, including serum amyloid A and tlr5 were identified as highly expressed after infection." (PMID 25620978, 2014). "Whether the reduction in TLR5 response post-exposure in this study can lead to an increased risk of infection in the larynx awaits investigation." (PMID 36333510, 2022). "Here, we provided evidence that post-THS infection is caused by the translocation and dissemination of certain strains of bacteria that originate from the host gut, and TLR5 has direct and significant effects on the composition of the gut microbial community and on mucosal immunity." (PMID 34840990, 2021). "However, we didn't replicate the infection in current study, although we found the significant association between TLR5 rs5744174 and GC risk." (PMID 28404962, 2017). "Moreover, recent clinical studies have shown the association of TLR2 and TLR5 gene polymorphisms with susceptibility to infection with M. tuberculosis and L. pneumophila, respectively." (PMID 22367599, 2012). "Therefore, flagellin-TLR5 interaction plays an important role in infection of pathogenic bacteria." (PMID 34912344, 2021). "TLR5 was initially associated with the recognition of H. pylori flagellin, but it seems that this bacterium has developed mechanisms to escape this recognition representing an important factor involved in the persistence of this infection and subsequent carcinogenesis." (PMID 30863783, 2019). "However, aflagellar serovars S. Pullorum and S. Gallinarum cause more severe infection than flagellar serovars in chicken because of aflagellar S. Typhimurium could avoid the TLR5 regulation of IL-1β expression and polymorphonuclear cell infiltration in gut." (PMID 20307324, 2010).
infection (continued). "The infection induced upregulation of chemoattractant (cklf) and respiratory burst effectors (rac2 and mpx), while suppressing inflammatory mediators (il8, tlr5, and clec4el)." (PMID 40821846, 2025). "Several studies have shown that the interaction between flagellin and TLR5 activates signaling pathways that lead to the production of IL-8, which recruits neutrophils to the infection site." (PMID 40005742, 2025). "A limitation of this study is the lack of in vivo validation of the role of hepatocyte TLR2:TLR6 and TLR5 in mediating the hepcidin response and subsequent hypoferremia during infection." (PMID 40182015, 2025). "The anticoagulant PROC associated positively with TLR1 and TLR9, but, with infection, became inversely correlated with TLR2, TLR5, and TLR8." (PMID 40825056, 2025). "Flagellins also activate TLR5 in intestinal epithelial cells, thereby inducing the secretion of IL-8, a cytokine that recruits neutrophils to the infection site." (PMID 40444793, 2025). "This is further supported by the observation that increased levels of TLR3 in platelets and TLR5 in leukocytes correlate with severity of infection and survival, while increased levels of leukocyte TLR7 are associated with reduced severity of infection." (PMID 40825056, 2025). "In Q. spinosa, both QsTLR5 and QsTLR5L exhibited a significant and sustained upregulation until 12 h post-infection, indicating that TLR5 functions similarly across vertebrates in immune responses triggered by bacterial pathogens." (PMID 40547361, 2025). "Transcriptomic analysis revealed that ΔfliL strain infection in hybrid groupers activated the TLR5-mediated NF-κB pathway and transcription factor AP-1 in the MyD88 pathway, resulting in an effective immune response." (PMID 39026675, 2024). "P. aeruginosa, a life threatening infection to CF patients, possesses immunostimulatory FLA that exacerbates pathogenic immunity in CF patients through sustained activation of toll-like receptor 5 (TLR5)." (PMID 39681187, 2024). "Among 35 articles, some of the studies demonstrated the response of TLR4 and TLR5 along with the TLR2 response during the infection of Leptospira spp./cell components." (PMID 39729468, 2024). "Genetic variants that influenced expression of immunologically relevant infection-related proteins, including ITGB6 and TLR5, predicted brain volume loss." (PMID 39143319, 2024). "In another pathogen, Burkholderia cenocepacia, the primary mechanism of avoiding host immunity is glycosylation of flagellin that reduces its recognition by the host TLR5, thus allowing it to evade immune surveillance to execute a successful infection." (PMID 37741057, 2023). "During infection, flagella can elicit a strong NFkB-mediated activation of the host immune response via Toll-like receptor 5 (TLR5) and a caspase-1-mediated response via the Nod-like receptor Ipaf." (PMID 36557761, 2022). "Bacterial suspensions or infection supernatants containing a proA deletion strain showed an increased TLR5 activation, indicating an important role of the zinc metalloprotease in counteracting pro-inflammatory properties of bacterial flagellin." (PMID 35625552, 2022). "Enrichment analyses of the differentially expressed genes revealed several central signatures following infection, including positive regulation of TLR5 signaling, which converged at the NF-kB level to modulate the proinflammatory cytokine response." (PMID 35386699, 2022). "Studies have shown that administration of flagellin (a TLR5 agonist), either concurrently or after bacterial infection, offers protection against infections with Pseudomonas aeruginosa and Streptococcus pneumoniae." (PMID 35986268, 2022). "Our results demonstrate that L. pneumophila Corby flagellin triggers TLR5-dependent immune response during infections of human lung tissue, which can be significantly reduced by expression of ProA." (PMID 35625552, 2022).
infection (continued). "To verify the intervention effect of VSP on TLRs, we examined the expression of TLR4 and TLR5 in 5637 (HTB-9) bladder epithelial cells after infection with UPEC." (PMID 36506014, 2022). "At both time points, infection with a proA-negative mutant resulted in significantly higher TLR5 activation than with the wild type." (PMID 35625552, 2022). "All these data demonstrate that extracellular ProA, which is also secreted by L. pneumophila during infections, is able to decrease TLR5 activation by cleavage of free monomeric flagellin in the surrounding medium of bacterial cells." (PMID 35625552, 2022). "Because the magnitude of the effect of the gene KO was comparable across these four TLRs, we posit that TLR2, TLR3, TLR4, and TLR5 are equally important in the macrophage response to L. pneumophila at least at the early stages of infection." (PMID 34280250, 2021). "More importantly, our experiments provided sufficient evidence supporting the contribution of the TLR5 pathway to post-THS infection." (PMID 34840990, 2021). "The transcripts of Tlr1, Tlr5, Tlr11, and Nod2, Nlrp1a, Naip2, and Nlrc4 were significantly higher in the Nlrp3−/− than wild-type mice on day 7 post-infection." (PMID 34690967, 2021). "In blood, the TLR5 expression level in ALD mice was significantly lower than that of the Pair group after infection." (PMID 34489943, 2021). "For instance, infection triggers co-expression of the cascade Toll-like receptor 5 (TLR5) and Myeloid differentiation primary response protein (MyD88), as previously reported in bony fish during bacterial infection." (PMID 33962693, 2021). "Compatible with the behavior of the MyD88 KO, TLR2 and TLR5 proved important for both IL-6 and TNFα secretion following infection with L. pneumophila." (PMID 34280250, 2021). "Using TLR transfected HEK-293 reporter cells, we have shown that P. histicola infection induced TLR2 signalling (at 4 hours) and importantly a rapid induction in TLR5 signalling, which was significantly reduced by the end of the 4 hour infection period." (PMID 33031374, 2020). "Previous study showed that TLR3 and TLR5 were upregulated at 24, 48 and 72 h post-infection in A549 pulmonary epithelial cells treated with Mtb, and the expression of neutrophil TLR2 is also increased in PTB patients." (PMID 32811479, 2020). "Infection of tumor cells with Mobilan results in constitutive autocrine/paracrine stimulation of the TLR5 signaling pathway, which leads to induction of an innate immune response followed by development of an adaptive antitumor immune response." (PMID 32292576, 2020). "With this infection, TLR5 expression in KO mice reached 78.2% of that observed in WT mice treated with AAV9-GFP." (PMID 33042267, 2020). "Infection of tumor cells with Mobilan in vivo establishes local paracrine/autocrine TLR5 signaling leading to induction of antitumor innate, and subsequently, adaptive immune responses in the tumor microenvironment." (PMID 32292576, 2020). "Having demonstrated the role of anti-FliC in mitigating TLR5 response, we next investigated their physiological significance in a natural infection model of S. typhimurium." (PMID 30838179, 2019). "As the first line of defense, ocular epithelium recognizes and responds to the motile pathogen via TLR5 which activates mucosal innate defense by producing proinflammatory cytokines leading to employ polymorphonuclear leukocytes (PMNs) to the infection site." (PMID 30944709, 2019). "Gene expression analysis of these TLRs in kidney and bladder homogenates revealed that only TLR5 was reduced in the bladder of Tacrolimus pre-treated mice upon infection." (PMID 30643171, 2019). "TLR2 and TLR5 expression differences have been noted in macrophage-like cells as well: infection with Borrelia burgdorferi upregulated both TLR2 and TLR5 expression in microglial cells, but only TLR2 was upregulated in monocytes." (PMID 31774834, 2019).
infection (continued). "Increased TLR5 surface expression was detected between 1 and 7 h post-infection in cells stimulated with LFliC." (PMID 29448958, 2018). "In this model, we also found that some genes exhibited a downward trend (e.g., Ptgs2, Rel, IL4r, CXCL1, CXCL2, TLR5, Nfatc3 and Egr2) in M. fortis after infection." (PMID 28900150, 2017). "In the context of infection, Pseudomonas aeruginosa flagellin elicits inflammatory response of corneal epithelium through the TLR5–nuclear factor κ-light-chain-enhancer of activated B cells (NF-κB) signaling pathway." (PMID 28273882, 2017). "When an infection with an invasive bacterial pathogen (such as S. Typhimurium) occurs, it generates the recognition by basolateral TLR5, which initiates an inflammatory immune response." (PMID 28293241, 2017). "Flagellin has been suggested as a key ligand in TLR5-mediated induction of the immune response to infection with Bcc bacteria." (PMID 28651010, 2017). "The opposing findings observed with flagellin, further suggest the protective role of the TLR5/NLRC4 axis in infection." (PMID 26972847, 2016). "Indirect evidence in favour of this can be found in a previous study where we observed tlr2 and tlr5-expressing cells migrating from secondary to primary lamellae during the first hours post-infection with V. vulnificus." (PMID 26207370, 2015). "The results for TLR5 showed a different pattern, insofar as its expression 3 and 6 h after infection with all four strains was similar to that observed in mock control." (PMID 23755130, 2014). "Amplitudes of A-wave and B-wave declined significantly both in wild type C57BL/6J and TLR5−/− eyes at 8 and 12 hours following infection with B. cereus." (PMID 24959742, 2014). "We therefore determined the cytolytic activity of NK cells against 51Cr-pulsed Yac-1 target cells in splenocytes harvested from the rflagellin- and PBS-treated WT or TLR5 KO mice on days 0 and 3 after mCMV infection." (PMID 24879439, 2014). "Nlrc4−/−/Tlr5−/− mice also had altered cytokine production at both 4 and 24 hours post infection when compared to wild-type (WT) and Nlrc4−/− mice." (PMID 23937571, 2013). "In conclusion, we demonstrated that infection with VREP-FliC-WT or VREP-FliC-D3 results in production of flagellin capable of signaling through TLR5." (PMID 23785460, 2013). "We next examined lung histology in WT, Nlrc4−/−, and Nlrc4−/−/Tlr5−/− mice at 1 and 3 days after infection and determined the percentage of inflamed airspace." (PMID 23937571, 2013). "At 4 h post-infection, the lungs of Nlrc4−/−/Tlr5−/− had decreased levels of tumor necrosis factor (TNF) compared to WT control lungs." (PMID 23937571, 2013). "The immune response of Nlrc4−/−, Nlrc4−/−/Tlr5−/−, and wild type C57Bl/6 mice was analyzed after in vivo infection with aerosolized Lp." (PMID 23937571, 2013). "We compiled all of the CFU data from experiments that we performed using WT, TLR5−/− and Casp1−/− mice in infections with WT, flagellin-null and flgM− Salmonella." (PMID 23977202, 2013). "This study investigates the effects of mannoprotein administration via a liquid diet on inflammatory response and TLR5 expression during intestinal tissue injury in a rat model of infection with Salmonella typhimurium." (PMID 20529359, 2010). "Previous studies have elegantly shown that while A/E pathogens induce host IL-8 expression through both MAPK and TLR5-dependent activation of NF-κB, translocated effectors also down-regulate IL-8 at early stages of infection." (PMID 20041225, 2009). "Our findings also demonstrate that severity of infection and survival correlate with different PRRs between these two blood components; in leukocytes, TLR5 positively correlated and TLR7 negatively correlated with ordinal score, while in platelets, TLR3 was positively correlated." (PMID 40825056, 2025).